COLEC12 (collectin subfamily member 12)
Description:
Scavenger receptor that displays several functions associated with host defense. Promotes binding and phagocytosis of Gram-positive, Gram-negative bacteria and yeast. Mediates the recognition, internalization and degradation of oxidatively modified low density lipoprotein (oxLDL) by vascular endothelial cells. Binds to several carbohydrates including Gal-type ligands, D-galactose, L- and D-fucose, GalNAc, T and Tn antigens in a calcium-dependent manner and internalizes specifically GalNAc in nurse-like cells. Also binds to sialyl Lewis X or a trisaccharide and asialo-orosomucoid (ASOR). May also play a role in the clearance of amyloid-beta in Alzheimer disease.
Synonyms: CL-P1; CLP1; NSR2; SCARA4; SRCL
Tractability: Antibody: its Gene Ontology location is reachable by antibodies, with high confidence; UniProt predicts a signal peptide or a membrane-spanning region. PROTAC: its protein half-life has been measured.
Gene: Protein-coding gene on chromosome 18 (316,737 to 500,722, reverse strand). Ensembl gene ENSG00000158270.
Subcellular location: Membrane
Subcellular location (Human Protein Atlas): Golgi apparatus; Vesicles; Cell Junctions
Pathways (Reactome):
Immune System: Immunoregulatory interactions between a Lymphoid and a non-Lymphoid cell
Vesicle-mediated transport: Scavenging by Class A Receptors
Gene Ontology:
Molecular function: low-density lipoprotein particle binding; pattern recognition receptor activity; protein binding; scavenger receptor activity; galactose binding
Biological process: defense response to bacterium; phagocytosis, recognition; plasma membrane raft organization; carbohydrate mediated signaling; defense response; extracellular matrix organization; innate immune response
Cellular component: endocytic vesicle membrane; extracellular matrix; membrane; plasma membrane
Genetic constraint (gnomAD): Loss-of-function variants: 18 observed, 44.47 expected, observed/expected ratio (o/e) 0.4, 90% interval 0.28 to 0.6. The upper end of that interval is the gene's LOEUF score, 0.6, which puts it in group 2 of 6, group 1 being the genes least tolerant of losing a copy. Missense variants: 638 observed, 756.58 expected, observed/expected ratio (o/e) 0.84, 90% interval 0.79 to 0.9. Synonymous variants: 303 observed, 304.02 expected, observed/expected ratio (o/e) 1, 90% interval 0.91 to 1.1.
Homologues: Orthologues: macaque COLEC12 (98% identical), chimpanzee COLEC12 (97% identical), dog COLEC12 (97% identical), rabbit COLEC12 (96% identical), pig COLEC12 (95% identical), guinea pig COLEC12 (94% identical), mouse Colec12 (92% identical), rat Colec12 (90% identical), tropical clawed frog colec12 (65% identical), zebrafish colec12 (51% identical). Paralogues in human: MARCO (15% identical), SCARA5 (15% identical), MSR1 (13% identical).